GABRG3 (gamma-aminobutyric acid type A receptor subunit gamma3)
Description:
Gamma subunit of the heteropentameric ligand-gated chloride channel gated by gamma-aminobutyric acid (GABA), a major inhibitory neurotransmitter in the brain (By similarity). GABA-gated chloride channels, also named GABA(A) receptors (GABAAR), consist of five subunits arranged around a central pore and contain GABA active binding site(s) located at the alpha and beta subunit interface(s) (By similarity). When activated by GABA, GABAARs selectively allow the flow of chloride across the cell membrane down their electrochemical gradient (By similarity).
Tractability: Small molecule: an approved drug acts on it; a high-quality ligand is known; it belongs to a druggable protein family. Antibody: its Gene Ontology location is reachable by antibodies, with high confidence; UniProt places it where antibodies can reach, with medium confidence; UniProt predicts a signal peptide or a membrane-spanning region. PROTAC: a small molecule that binds it is known.
Safety:
Unwanted effects reported when the protein is acted on. In parentheses: how it was acted on, where the effect was seen, and who reports it.
ataxia (activation, acute dosing; central nervous system, cardiovascular; source: Lynch et al. (2017))
convulsions (inhibition, acute dosing; central nervous system, cardiovascular; source: Lynch et al. (2017))
decreased anxiety (activation, acute dosing; central nervous system, cardiovascular; source: Lynch et al. (2017))
decreased blood pressure (activation, acute dosing; central nervous system, cardiovascular; source: Lynch et al. (2017))
decreased body temperature (activation, acute dosing; central nervous system, cardiovascular; source: Lynch et al. (2017))
decreased cardiac contractility (activation, acute dosing; central nervous system, cardiovascular; source: Lynch et al. (2017))
decreased convulsions (activation, acute dosing; central nervous system, cardiovascular; source: Lynch et al. (2017))
decreased locomotor activity (activation, acute dosing; central nervous system, cardiovascular; source: Lynch et al. (2017))
decreased memory (activation, acute dosing; central nervous system, cardiovascular; source: Lynch et al. (2017))
decreased pain (activation, acute dosing; central nervous system, cardiovascular; source: Lynch et al. (2017))
decreased sleep (inhibition, acute dosing; central nervous system, cardiovascular; source: Lynch et al. (2017))
drug abuse/dependence (activation, acute dosing; central nervous system, cardiovascular; source: Lynch et al. (2017))
increased cardiac output (activation, acute dosing; central nervous system, cardiovascular; source: Lynch et al. (2017))
increased eating (activation, acute dosing; central nervous system, cardiovascular; source: Lynch et al. (2017))
increased respiratory rate (activation, acute dosing; central nervous system, cardiovascular; source: Lynch et al. (2017))
increased sleep (activation, acute dosing; central nervous system, cardiovascular; source: Lynch et al. (2017))
muscle relaxation (activation, acute dosing; central nervous system, cardiovascular; source: Lynch et al. (2017))
tardive dyskinesia (source: ClinPGx)
Gene: Protein-coding gene on chromosome 15 (26,971,181 to 27,541,984, forward strand). Ensembl gene ENSG00000182256.
Subcellular location: Postsynaptic cell membrane; Cell membrane
Subcellular location (Human Protein Atlas): Microtubules; Plasma membrane; Nucleoli
Pathways (Reactome):
Neuronal System: GABA receptor activation
Signal Transduction: Signaling by ERBB4
Gene Ontology:
Molecular function: GABA-A receptor activity; GABA-gated chloride ion channel activity; chloride channel activity; extracellular ligand-gated monoatomic ion channel activity; monoatomic ion channel activity; transmembrane signaling receptor activity; transmitter-gated monoatomic ion channel activity involved in regulation of postsynaptic membrane potential
Biological process: chloride transmembrane transport; inhibitory synapse assembly; synaptic transmission, GABAergic; chloride transport; gamma-aminobutyric acid signaling pathway; monoatomic ion transmembrane transport; monoatomic ion transport; regulation of postsynaptic membrane potential; response to xenobiotic stimulus
Cellular component: plasma membrane; dendrite membrane; GABA-A receptor complex; postsynapse; GABA-ergic synapse; membrane; postsynaptic membrane; synaptic membrane
Genetic constraint (gnomAD): Loss-of-function variants: 18 observed, 44.5 expected, observed/expected ratio (o/e) 0.4, 90% interval 0.28 to 0.6. The upper end of that interval is the gene's LOEUF score, 0.6, which puts it in group 2 of 6, group 1 being the genes least tolerant of losing a copy. Missense variants: 329 observed, 493.26 expected, observed/expected ratio (o/e) 0.67, 90% interval 0.61 to 0.73. Synonymous variants: 188 observed, 189.97 expected, observed/expected ratio (o/e) 0.99, 90% interval 0.88 to 1.12.
Homologues: Orthologues: chimpanzee GABRG3 (99% identical), macaque GABRG3 (99% identical), pig GABRG3 (99% identical), dog GABRG3 (98% identical), rabbit GABRG3 (97% identical), mouse Gabrg3 (96% identical), rat Gabrg3 (96% identical), tropical clawed frog gabrg3 (85% identical). Paralogues in human: GABRG2 (67% identical), GABRG1 (66% identical), GABRE (46% identical), GABRA4 (42% identical), GABRA6 (42% identical), GABRA5 (41% identical), GABRA1 (41% identical), GABRA3 (41% identical), GABRA2 (40% identical), GLRA2 (34% identical), GABRB2 (34% identical), GLRA3 (33% identical), and 33 more.
Diseases named in the same sentence as GABRG3 in open-access papers:
GABRG3 is named in the same sentence as 35 diseases in open-access papers, as found by Europe PMC text mining. Sharing a sentence is not in itself a finding about the gene and the disease. The quoted sentences say what the papers report.
autism (11 papers, 2013 to 2024). Persistent deficits in social interaction and communication and interaction as well as a markedly restricted repertoire of activity and interest as well as repetitive patterns of behavior. "Under the recessive model, the C allele of rs7180500 in GABRG3 also displayed a nominal association with autism (rs7180500: C>A, Z = 2.798, p = 0.0052)." (PMID 30108208, 2018). "Transmission disequilibrium tests (TDT) for 16 single nucleotide polymorphisms (SNPs) in GABAA receptor genes cluster indicated that 2 SNPs in GABRG3 were nominally associated with autism in Caucasians19." (PMID 30108208, 2018). "Our study indicated that the C allele of rs7180500 in GABRG3 was significantly associated with autism in 512 autism trios." (PMID 30108208, 2018). "Our study suggested that common variants and rare variants in GABRG3 were significantly associated with autism." (PMID 30108208, 2018). "Our results showed that the C allele of rs7180500 in GABRG3 was a risk variant for autism (p = 0.00057)." (PMID 30108208, 2018). "Nine SNPs (rs8025849 in NIPA1, rs3812922 in NIPA2, rs1009153 and rs2289818 in CYFIP1, rs8037745 in SNRPN, rs12438141 and rs1863467 in GABRB3, rs7403021 and rs7180500 in GABRG3) were nominally associated with autism under the recessive model (p < 0.05)." (PMID 30108208, 2018). "In this study, we detected that both common variant (rs7180500) and rare variant rs201602655 (p.Val233Met) in GABRG3 were associated with autism in Chinese Han population." (PMID 30108208, 2018). "As for rs201602655 (p.Val233Met) in GABRG3, one autistic child (1/512) presented this de novo heterozygous mutation and 8 children affected with autism (8/512) were inherited from their parents (four were maternal and the others were paternal, all heterozygotes)." (PMID 30108208, 2018). "Our results might indicate that the rare variants detected in GABRG3 might contribute to the increased risk of autism." (PMID 30108208, 2018). "However, other top DEGs including CNTNAP4, SLC1A2, and GABRG3 have also been shown to underly irregular firing patterns in the context of epilepsy or autism and could be contributing to the disease mechanism." (PMID 38280846, 2024). "Gabrg3, which encodes the γ3 subunit of GABAA receptors, has been associated with an increased risk of developing alcoholism, autism, and other psychiatric disorders." (PMID 38388464, 2024). "Therefore, GABAA receptor genes cluster including GABRG3 might play a role in the etiology of autism." (PMID 30108208, 2018). "Furthermore, the functional evidence indicated that abnormal expression of GABRG3 and other GABAA receptors subunits genes could serve as susceptibility factors for autism." (PMID 30108208, 2018). "We detected two rare variants rs201602655 (p.Val233Met) and rs201427468 (p.Pro365Ser) in GABRG3 in 2 autistic children and six rare single nucleotide variants (c.−693A>T, c.*417C>T, c.*704A>T, c.*1730G>A, c.*2583C>T, c.*3536T>C) in GABRB3 in 6 of 96 patients affected with autism." (PMID 30108208, 2018).
epilepsy (8 papers, 2016 to 2024). A brain disorder characterized by episodes of abnormally increased neuronal discharge resulting in transient episodes of sensory or motor neurological dysfunction, or psychic dysfunction. "We found that variants in the epilepsy-associated genes GABRA1, GABRB3 and GABRG2 were mainly present in the ESP variants, but the GEC cohort contained epilepsy-associated GABRA6, GABRB1, and GABRB2 and non-epilepsy- associated GABRA4, GABRA5, and GABRG3 genes." (PMID 27622563, 2016).
autism spectrum disorder (6 papers, 2016 to 2024). A spectrum of developmental disorders that includes autism, and Asperger syndrome. "Using WGCNA methods, we identified Gabrg3 as one of the hub genes, which has a strong association with Autism Spectrum Disorder and alcohol dependence." (PMID 38388464, 2024). "GABAA receptor subunit genes GABRB3, GABRA5, and GABRG3 located on chromosome 15q11-q13 have been implicated in the etiology of autistic spectrum disorders (ASD)." (PMID 28607477, 2017).
Angelman syndrome (5 papers, 2016 to 2022). A neurogenetic disorder characterized by severe intellectual deficit and distinct facial dysmorphic features. "Moreover, a cluster of genes in the BTA21 (GABRG3, MAGEL2, MKRN3, NDN, SNRPN, and SNURF) was significantly associated (FDR = 1.07 × 10−6) with the Prader-Willi and Angelman syndromes pathway in the PPI analysis." (PMID 35692843, 2022). "In Angelman syndrome, a disorder highly penetrant for ID, beta power is reduced in cases caused by 15q11-q13 deletion relative to cases with etiologies that mainly impact UBE3A, suggesting a positive relationship between beta power and GABRB3/GABRA5/GABRG3 copy number." (PMID 31312421, 2019).
alcohol dependence (4 papers, 2020 to 2024). Physical and psychological dependence on alcohol. "Moreover, it has been demonstrated that GABRG3 contained a binding sites of Benzodiazepine, which can be used to treat alcoholism and alcohol withdrawal symptoms." (PMID 34417442, 2021).
breast carcinoma (3 papers, 2022 to 2025). "We found that the seven GABAA receptor subunits were upregulated in TNBC breast cancers, including GABRA1, GABRA5, GABRD, GABRE, GABRP, GABRQ, and GABRG3." (PMID 36923530, 2023).
Obesity (3 papers, 2020 to 2022). Accumulation of substantial excess body fat. "The results revealed that 18 of the DMR genes were associated with addiction and obesity (ADCY3; ADCY9; ATF4; CDK5R1; CHRNB2; GABRD; GABRG3; GNB1; GNB3; GRK5; HDAC4; HDAC9; MAP2K1; PDE11A; PDE2A; PDE3A; PPP1CA; SLC6A3)." (PMID 34389046, 2021).
Prader-Willi syndrome (2 papers, 2016 to 2019). "In the future, we will examine Prader Willi syndrome to further disentangling the electrophysiological roles of UBE3A and GABRB3/GABRA5/GABRG3." (PMID 31312421, 2019). "Similarly, Gamma-aminobutyric acid A receptor gamma 3 (GABRG3) is an early childhood obesity gene reported in Prader-Willi syndrome, but, direct experimental evidence is not known." (PMID 26886906, 2016).
psychosis (2 papers, 2021 to 2022). "Other genes and snoRNAs that might play a role in the onset of psychosis are GABRG3, NDN, CYFIP1 and SNORD115." (PMID 35887798, 2022).
schizophrenia (2 papers, 2014 to 2025). A major psychotic disorder characterized by abnormalities in the perception or expression of reality. "On the other hand, the antagonists targeting GABRG-3, GABRG-4, DRD5, ADR -A1D/–B2, CHRM-3, and SLC6A4 (all elevated by FD) are under investigation for treating bipolar disorder and schizophrenia." (PMID 24632812, 2014).
Alzheimer disease (1 paper, 2022). A progressive, neurodegenerative disease characterized by loss of function and death of nerve cells in several areas of the brain leading to loss of cognitive function such as memory and language. "An association between GABRG3 and several chronic diseases, including Alzheimer’s disease, ovarian carcinoma, and non-melanoma carcinoma, was also reported in other previous GWAS." (PMID 35624665, 2022).
colon adenocarcinoma (1 paper, 2022). "Ling Yan and colleagues showed that overexpression of GABRA2, GABRA3, GABRB3, GABRG2, GABRG3, GABRD, and GABRE might be diagnostic for colon adenocarcinoma." (PMID 35565356, 2022).
colon cancer (1 paper, 2024). "However, irrespective of whether expression of GABAA or GABAB receptor subunits were altered in colon cancer, expression of particular receptor subtypes (GABRA1, GABRA5, GABRD, GABRE, GABRG1, GABRG3, GABBR1, and GABBR2) was significantly associated with poor clinical outcome." (PMID 38886975, 2024).
diabetes (1 paper, 2023). "GABRG3-rs2192224, rs2499511, LOC105379144-rs12719264 were replicated in the UKB cohort, showing consistent effects with previous results, demonstrating their potential as biomarkers for albuminuria in individuals with diabetes." (PMID 37446387, 2023).
cancer (4 papers, 2011 to 2023). A tumor composed of atypical neoplastic, often pleomorphic cells that invade other tissues. "Results showed that GABRA3, SLC6A3, GABRQ, SCN4A, and GABRG3 were overexpressed in cancer compared with normal liver tissues." (PMID 35401884, 2022). "Expression of GABRG3, GABRQ, GABRE, and GABRR2 is correlated with inhibition of growth phenotypes in cell lines and with favorable patient outcomes (Broad Institute of MIT & Harvard, firebrowse.org), while expression of other transcripts (GABRB2, GABRP) is associated with cancer progression." (PMID 33187258, 2020).
psychiatric disorder (2 papers, 2021 to 2024). A disorder characterized by behavioral and/or psychological abnormalities, often accompanied by physical symptoms. "Moreover, Gabrg3 is located in 15q11-q13, an intriguing locus linked to multiple psychiatric disorders, and is speculated to be an imprinted gene with maternal silencing and paternal expression." (PMID 38388464, 2024).
GABRG3 also shares sentences with these, for which no sentence is quoted: alcoholism (2 papers); Anxiety (2); neurodevelopmental disorder (2); amyotrophic lateral sclerosis (1); bipolar disorder (1); CNS tumors (1); colorectal cancer (1); depression (1); developmental delay (1); fragile X syndrome (1); Hypertension (1); learning disabilities (1); medulloblastoma (1); muscular dystrophy (1); myopia (1); neurological disorders (1); ovarian carcinoma (1); panic disorder (1); tuberous sclerosis (1).